AVP (arginine vasopressin)
Diseases named in the same sentence as AVP in open-access papers (continued):
Sharing a sentence is not in itself a finding about the gene and the disease.
enuresis (4 papers, 2015 to 2025). An elimination disorder characterized by urinary incontinence, whether involuntary or intentional, which is not due to a medical condition and which occurs at or beyond an age at which continence is expected (usually 5 years). "Similarly, in the present case, lithium‐induced renal enuresis may have contributed to decreased renal sensitivity to AVP, leading to chronic secretory stimulation of the posterior pituitary gland." (PMID 40821911, 2025).
Hepatic failure (4 papers, 2018 to 2025). "In a literature review by Robert W. Shrier, it was noted that third spacing/volume overload in both cardiac and liver failure is largely driven by the non-osmotic activation of the arginine vasopressin as well as the RAAS." (PMID 39982244, 2025). "When compared to responders, non-responders had higher rates of hepatic failure (19.3 vs. 14.3%; P = 0.04), lower MAP values (65 ± 12 vs. 69 ± 12 mmHg; P < 0.001) and higher lactate concentrations (5.4 ± 4.8 vs. 4.0 ± 3.6 mmol/L; P < 0.001) at AVP initiation." (PMID 29511951, 2018).
hyperprolactinemia (4 papers, 2023 to 2026). Abnormally high level of prolactin in the blood. "AVP deficiency and hyperprolactinemia may be partially due to thickening of the pituitary stalk, which may have resulted in impairment of AVP and dopamine, a prolactin-suppressing hormone." (PMID 38769570, 2024).
intrauterine growth restriction (4 papers, 2016 to 2023). "Chronic stress is associated with chronically elevated AVP/copeptin levels in rodent as well as human fetuses suffering from intrauterine growth restriction." (PMID 27532032, 2016). "AVP exerts its physiological functions via V1a and V2 receptors; the activation of these receptors has been implicated in proteinuria, renal glomerular endotheliosis, and intrauterine growth restriction, respectively." (PMID 37043097, 2023). "Despite translatable effects on the fetus and placenta (e.g., intrauterine growth restriction, adverse placental outcomes), the impact of increased maternal AVP on offspring neurodevelopment remains poorly understood and is the focus of this study." (PMID 33510137, 2021).
malaria (4 papers, 2004 to 2021). Malaria is a serious and sometimes fatal disease caused by a parasite that commonly infects a certain type of mosquito which feeds on humans. "Conversely, during inappropriate AVP release, the emphasis of therapy should perhaps be more on aggressive anti-malaria treatment, given the association with a stronger pro-inflammatory cytokine response." (PMID 22280539, 2012). "In hyponatraemic patients with imported malaria, AVP release was uniformly increased and was either appropriate or inappropriate." (PMID 22280539, 2012). "In fact, in seven of 13 hyponatraemic malaria patients an inappropriate release of AVP appeared to be present." (PMID 22280539, 2012). "This suggests active water reabsorption by the kidneys in malaria patients with inappropriate AVP release." (PMID 22280539, 2012). "Because urine sodium is a major determinant of urine osmolality, a lower urine sodium would, therefore, result in a lower urine osmolality in malaria patients with appropriate AVP release." (PMID 22280539, 2012). "Data from the sub-study suggested inappropriate AVP release in seven of 13 hyponatraemic malaria patients; these patients had significantly higher body temperatures on admission." (PMID 22280539, 2012). "The distinction between appropriate and inappropriate AVP release in hyponatraemic malaria patients may be relevant with regard to selecting the optimal intravenous fluid regimen." (PMID 22280539, 2012). "Although the exact trigger for inappropriate AVP release remains unknown, the higher body temperatures, correlations with C-reactive protein and long normalization times of serum sodium, suggest an important role of the host inflammatory response to the invading malaria parasite." (PMID 22280539, 2012). "Because previous studies did not separate hyponatraemic malaria patients on the basis of appropriate or inappropriate AVP secretion, future studies are necessary to give clinical guidance." (PMID 22280539, 2012).
Meniere disease (4 papers, 2011 to 2023). A disease of the inner ear (labyrinth) that is characterized by fluctuating sensorineural hearing loss; tinnitus; episodic vertigo; and aural fullness. "Therefore, the suggestion that high levels of plasma stress hormone AVP in patients with Meniere's disease could cause vertigo attacks or stressful vertigo attacks has remained controversial." (PMID 34659087, 2021). "To elucidate the scientific relationship in neuro-endocrinology between Meniere's disease and stress, we examined the surgical results of endolymphatic sac drainage surgery and changes in stress-induced plasma arginine-vasopressin levels." (PMID 34659087, 2021). "Further we showed that Claudin 4 in the ES is a target of arginine-vasopressin (AVP), a hormone elevated in Menière’s disease." (PMID 28374851, 2017).
mental disorder (4 papers, 2018 to 2023). A disease that has its basis in the disruption of mental process. "Likewise, previous studies have also found a potential association between altered OXT and AVP plasma levels with the risk of suffering mental disorders in pregnancy, especially PPD." (PMID 37373400, 2023). "Alterations in OXT, AVP and their receptors are related to different obstetric complications and mental disorders related to pregnancy like postpartum depression (PPD) or preeclampsia." (PMID 37373400, 2023).
migraine (4 papers, 2021 to 2024). "It is intriguing that AVP is an output of hypothalamic neurons that influences trigeminal, spinal and central brain areas associated with migraine." (PMID 36456902, 2022). "AVP is considered as a stress hormone and is released in response to pain and stress, therefore having clear association with migraine pathophysiology." (PMID 36456902, 2022). "In addition, some migraine precipitators (stress, ethanol, etc.)cause decreased AVP secretion and bioavailability, while some migraine-improving factors (tricyclic antidepressants, sleep, etc.)are associated with an increase in AVP." (PMID 38392617, 2024). "It is possible that the AVP secretion has nothing directly to do with migraine, but, since the highest levels of AVP during a migraine attack may be associated with emesis and vomiting, hypovolemia and nausea without vomiting trigger AVP release." (PMID 38392617, 2024). "Since AVP is considered a stress hormone and is released in response to pain and stress, it therefore may have association with migraine pathophysiology." (PMID 36456902, 2022). "In conclusion, we showed that AVP and its receptors were expressed in migraine-related areas within the male brain, and in female and male TG, predominantly in neuronal cytoplasm." (PMID 36456902, 2022). "Comparing the distribution of AVP with the “migraine generator” and CGRP, OT/OTR and estrogen receptors, showed that almost all of the peptides (including AVP) were found in migraine-related areas such as cortex, cerebellum, hypothalamus, amygdala and pons." (PMID 36456902, 2022). "While much data has been published regarding AVP in the brain, our focus here is on migraine-related regions." (PMID 36456902, 2022). "Elevated levels of AVP may be responsible for the facial pallor, antidiuresis, and coagulation abnormalities occasionally observed in migraine." (PMID 38392617, 2024). "Finally, the associations of migraines with circadian or circannual rhythm-related neuropeptides other than PACAP, such as VIP, GRP, AVP, NMS, and DA, were described." (PMID 37373239, 2023). "Thus, in light of the key role of initiation and maintenance of migraine attacks by the hypothalamus, it is particularly fascinating that AVP is an output that influences trigeminal, spinal and central brain areas associated with migraine." (PMID 36456902, 2022). "Thus, the AVP system has many ways to modulate migraine pathophysiology." (PMID 38392617, 2024). "Specifically, AVP, in response to stress and pain, may be relevant to migraine pathophysiology." (PMID 38392617, 2024). "Therefore, AVP and its receptors might be components that contribute to the hormonal influence on migraine in women." (PMID 36456902, 2022). "GRP, AVP, GABA, and NMS have been poorly studied in migraine patients." (PMID 37373239, 2023). "Interestingly, we found AVP expression, however weaker compared to other brain areas, in Sp5 (spinal trigeminal nucleus caudalis; TNC), which constitutes an important part of the pain pathways activity in migraine attacks." (PMID 36456902, 2022). "The degree of expression of AVP and AVP receptors, especially V1bR, in the CNS is complex and suggestive of many different brain functions, which does not exclude a possible role in migraine." (PMID 36456902, 2022).
motion sickness (4 papers, 2014 to 2022). sympton caused by motion, as sea sickness, train sickness, car sickness, air sickness, or space motion sickness. "Arginine vasopressin (AVP) is considered to be an etiologic hormone in motion sickness (MS)." (PMID 26651338, 2015). "Accordingly, AVP has been considered to be an etiologic hormone in motion sickness." (PMID 26651338, 2015). "It is well known that levels of AVP and cortisol are extensively increased in motion sickness; therefore, the CT-proAVP and cortisol values of the motion-sick subjects were excluded from the statistical analysis of the blood hormones, and individual data are shown instead." (PMID 24623065, 2014). "The ability of AVP and ADr (especially together) to increase myogenic contractions is consistent with AVP‐induced EGG tachygastria, a role for catecholamines in inducing tachygastria during motion sickness and with electrical tachygastria during nausea." (PMID 36068676, 2022). "In addition to behavioral reactions, motion sickness also induced temporal changes in concentration of blood hormones including adrenocorticotropic hormone (ACTH), corticosterone, norepinephrine, epinephrine, β-endorphin and arginine-vasopressin (AVP) in rodents." (PMID 28261089, 2017).
personality disorder (4 papers, 2018 to 2025). A diverse category of psychiatric disorders characterized by behavior that deviates markedly from the expectations of the individual's culture; this pattern of deviation is pervasive and inflexible and is stable over time. "Human studies further support this, showing that higher cerebrospinal fluid levels of AVP correlate with increased aggression in individuals with personality disorders, highlighting AVP’s broader role in aggressive behaviours." (PMID 40011829, 2025). "Regarding the role of AVP in human aggression, it has demonstrated that the cereborspinal fluid level of AVP was positively correlated with the aggressive life histories in individuals with personality-disorder." (PMID 30158862, 2018).
post-traumatic stress disorder (4 papers, 2020 to 2023). An anxiety disorder precipitated by an experience of intense fear or horror while exposed to a traumatic (especially life-threatening) event. "The serum concentration of AVP is higher in more aggressive dogs and humans with post-traumatic stress disorder." (PMID 32917190, 2020). "AVP is regarded a potential biomarker for posttraumatic stress disorder or anxiety, which may contribute to physical well-being and long-term-outcome in critical care patients." (PMID 36434506, 2022). "AVP secretion within the central nervous system is considered crucial for maintaining a mental balance, and disturbances in the central neuropeptide system, in which AVP plays an important role, may contribute to the development of psychiatric issues like post-traumatic stress disorder." (PMID 36434506, 2022). "According to one human study, elevated levels of plasma AVP in patients with post-traumatic stress disorder compared to both traumatised and healthy non-traumatised controls were reported." (PMID 32917190, 2020).
prostate carcinoma (4 papers, 2020 to 2025). A carcinoma that arises from epithelial cells of the prostate gland. "The treatment of Castration-resistant prostate cancer (CRPC) cells with the AVPR1A ligand, arginine vasopressin (AVP), activated cAMP response element-binding protein (CREB) via the RAS-MAPK transduction cascade." (PMID 38028758, 2023).
Renal cyst (4 papers, 2018 to 2019). A fluid filled sac in the kidney. "In rats, the congenital deficiency of AVP completely abrogated renal cyst formation and growth, providing compelling evidence that AVP has a critical role in cystogenesis and that its inhibition at an early stage of disease could markedly reduce the risk of developing ESKD in ADPKD." (PMID 29358433, 2018). "Increasing the intake of water attenuates AVP release, and has been hypothesised to be an easily-accessible and safe therapeutic intervention to reduce renal cyst growth in PKD." (PMID 30601830, 2019). "The PCK AVP−/− rats have lower renal cAMP level and show a marked reduction in renal cysts." (PMID 31024067, 2019). "Furthermore, pharmacological receptor antagonists of AVP, such as tolvaptan, reduce renal cyst growth and the decline in renal function in both experimental and human PKD, confirming the importance of AVP in renal cyst growth." (PMID 30601830, 2019). "As increased fluid intake decreases the release of AVP, it has been hypothesised that it may slow the growth of renal cysts in ADPKD." (PMID 30096903, 2018). "Despite evidence indicating a potential relationship between levels of arginine vasopressin and renal cyst growth in ADPKD, no simple clinical tools to assess fluid intake in this population are available." (PMID 30096903, 2018).
Addison's disease (3 papers, 2010 to 2023). "The association of IIH with Addison's disease is possibly secondary to increased serum and CSF arginine vasopressin peptide (AVP) in a glucocorticoid deficient state." (PMID 20170523, 2010). "Thus it is possible that increased serum, and possibly CSF AVP may mediate IIH in Addison's disease." (PMID 20170523, 2010).
adenoma (3 papers, 2013 to 2025). A neoplasm arising from the epithelium. "For this reason, we focused further on AVP and concurrently measured AVP effects in long-term adrenal cell cultures of non-AIMAH origin (i.e. 3 normal adrenals, 1 ACTH-dependent hyperplasia, 3 adenomas and 4 carcinomas)." (PMID 24034279, 2013).
amyotrophic lateral sclerosis (3 papers, 2011 to 2019). Amyotrophic lateral sclerosis (ALS) is a neurodegenerative disease characterized by progressive muscular paralysis reflecting degeneration of motor neurons in the primary motor cortex, corticospinal tracts, brainstem and spinal cord. "There is now extensive evidence showing that the AVP system is impaired in several neuromuscular diseases, such as amyotrophic lateral sclerosis and multiple sclerosis, suggesting that AVP may act as a physiologic factor in skeletal muscle homeostasis." (PMID 24971321, 2014). "Moreover, the role of AVP as a physiological factor in skeletal muscle homeostasis is also suggested by evidence showing that the AVP system is impaired in several neuromuscular diseases such as amyotrophic lateral sclerosis and multiple sclerosis." (PMID 31461843, 2019).
atherosclerosis (3 papers, 2016 to 2022). A disease characterized by the build-up of fatty material and calcium deposition in the arterial wall resulting in partial or complete occlusion of the arterial lumen. "Copeptin is a peptide which derives from the same precursor of arginine vasopressin and is considered a useful biomarker of several pathologic conditions such as myocardial infarction, atherosclerosis and ischemic stroke." (PMID 35628528, 2022). "In this study, the cardiovascular safety of the selective V1A receptor agonist selepressin and AVP was investigated in comparison with that of the septic shock standard of care NE in a well-established rabbit model of early-stage atherosclerosis." (PMID 27788216, 2016). "Here, selepressin and AVP treatments did not display relevant cardiovascular risk in early-stage rabbit atherosclerosis." (PMID 27788216, 2016).
birth asphyxia (3 papers, 2017 to 2024). "Here we show for the first time that normal rat birth is also accompanied by an AVP surge, and that the fetal AVP surge is further enhanced in a model of birth asphyxia, based on exposing 6-day old rat pups to a gas mixture containing 4% O2 and 20% CO2 for 45 min." (PMID 29403357, 2018). "A massive surge of AVP release takes place during normal vaginal birth in response to activation of the fetal HPA-axis, and this release is further accentuated by various kinds of stressors, including birth asphyxia." (PMID 28931055, 2017).
cerebrovascular disease (3 papers, 2017 to 2026). "Because all patients in our study had no cerebral pathology, it is not certain how SjvO2 and rSCO2 will respond after changing to the BCP with AVP pretreatment in patients with impaired CBF autoregulation or cerebrovascular disease." (PMID 28558702, 2017).
chronic obstructive pulmonary disease (3 papers, 2006 to 2019). A chronic and progressive lung disorder characterized by the loss of elasticity of the bronchial tree and the air sacs, destruction of the air sacs wall, thickening of the bronchial wall, and mucous accumulation in the bronchial tree. "In a cohort study of 385 patients, elevated levels of ADM, AVP, and ANP were all associated with increased risk of death in patients with stable chronic obstructive pulmonary disease (COPD)." (PMID 31022834, 2019).
deficiencies (3 papers, 2016 to 2025). "Patient number 14 had gonadotropin and GH deficiencies and patient 15 had gonadotropin and AVP deficiencies." (PMID 27678103, 2016). "On hormone assessment, all patients had both AVP and GH deficiencies." (PMID 39420885, 2024).
edema (3 papers, 2017 to 2023). An abnormal accumulation of fluid beneath the skin, or in one or more cavities of the body. "Arginine Vasopressin (AVP) is an important factor contributing to the pathophysiology of cerebral edema following, for example, ischemic brain injury." (PMID 36498538, 2022). "Some researchers suggest that electrolytes disrupt the normal function of cells, while others suggest that they may elevate arginine vasopressin levels, leading to pulmonary edema and, eventually, BPD." (PMID 36357648, 2023). "However, the symptoms of hyperammonemia, a prerequisite for the development of brain edema in fulminant ALF, become more pronounced in the presence of AVP." (PMID 29216295, 2017).
Hypervolemia (3 papers, 2018 to 2025). An increase in the amount of intravascular fluid, particularly in the volume of the circulating blood. "Diuretics are the mainstay of treatment of fluid overload but can exacerbate HN by decreasing intravascular volume (leading to increased AVP release) and only blocking sodium reabsorption, leaving continued free-water absorption unopposed." (PMID 30363747, 2018).
pituitary tumor (3 papers, 2014 to 2026). A benign or malignant neoplasm affecting the pituitary gland. "SV40 large T antigen overexpression using another promoter, the arginine vasopressin (AVP) gene promoter, also resulted in pituitary tumors although these tumors were composed of undifferentiated somatotroph cells." (PMID 25136513, 2014).
Takotsubo syndrome (3 papers, 2013 to 2022). "This suggests the arginine-vasopressin system is not implicated in Takotsubo syndrome or it may be supressed or even exhausted." (PMID 34095448, 2021).
type 1 diabetes (3 papers, 2017 to 2024). "Reduced AVP secretion in individuals with type 1 diabetes explains part of their defective CRR." (PMID 38017352, 2024).
-hypophysis (2 papers, 2023 to 2025). "In general, the SIADH has been reported as the most common cause of DPH, the mechanism of which is intraoperative trauma to the neuro-hypophysis that contributes to uncontrolled arginine vasopressin (ADH) release, leading to water retention." (PMID 41409605, 2025).